VIRMA (vir like m6A methyltransferase associated)
Description:
Associated component of the WMM complex, a complex that mediates N6-methyladenosine (m6A) methylation of RNAs, a modification that plays a role in the efficiency of mRNA splicing and RNA processing. Acts as a key regulator of m6A methylation by promoting m6A methylation of mRNAs in the 3'-UTR near the stop codon: recruits the catalytic core components METTL3 and METTL14, thereby guiding m6A methylation at specific sites. Required for mRNA polyadenylation via its role in selective m6A methylation: m6A methylation of mRNAs in the 3'-UTR near the stop codon correlating with alternative polyadenylation (APA).
Synonyms: KIAA1429; MSTP054; DKFZP434I116; fSAP121
Tractability: PROTAC: ubiquitination databases record sites on it.
Gene: Protein-coding gene on chromosome 8 (94,487,689 to 94,553,529, reverse strand). Ensembl gene ENSG00000164944.
Subcellular location: Nucleus speckle; Nucleus, nucleoplasm; Cytoplasm
Subcellular location (Human Protein Atlas): Nuclear bodies; Nucleoplasm
Gene Ontology:
Molecular function: protein binding; RNA binding
Biological process: mRNA processing
Cellular component: nuclear body; nuclear speck; nucleoplasm; RNA N6-methyladenosine methyltransferase complex; cytoplasm; nucleus
Genetic constraint (gnomAD): Loss-of-function variants: 45 observed, 131.51 expected, observed/expected ratio (o/e) 0.34, 90% interval 0.27 to 0.44. The upper end of that interval is the gene's LOEUF score, 0.44, which puts it in group 1 of 6, group 1 being the genes least tolerant of losing a copy. Missense variants: 1,389 observed, 1,821.1 expected, observed/expected ratio (o/e) 0.76, 90% interval 0.73 to 0.8. Synonymous variants: 582 observed, 633 expected, observed/expected ratio (o/e) 0.92, 90% interval 0.86 to 0.99.
Homologues: Orthologues: chimpanzee VIRMA (99% identical), macaque VIRMA (99% identical), dog VIRMA (98% identical), rabbit VIRMA (98% identical), pig VIRMA (98% identical), mouse Virma (96% identical), rat Virma (95% identical), guinea pig VIRMA (92% identical), tropical clawed frog virma (73% identical), zebrafish virma (58% identical), Drosophila melanogaster vir (26% identical).
Diseases named in the same sentence as VIRMA in open-access papers:
VIRMA is named in the same sentence as 102 diseases in open-access papers, as found by Europe PMC text mining. Sharing a sentence is not in itself a finding about the gene and the disease. The quoted sentences say what the papers report.
breast carcinoma (56 papers, 2019 to 2025). "Studies have shown that VIRMA is aberrantly overexpressed in more than 20 types of malignant tumors, including liver cancer, breast cancer, and lung cancer, and is significantly associated with chromosome 8q amplification and poor prognosis." (PMID 40723784, 2025). "Collectively, we observe a high frequency of VIRMA amplification, which is associated with higher expression of VIRMA across all subtypes of breast cancers." (PMID 37208522, 2023). "VIRMA could promote breast cancer proliferation and metastasis in vivo and in vitro, which indicated that VIRMA could promote breast cancer progression and was associated with pathogenesis." (PMID 33731118, 2021). "VIRMA has been primarily investigated in the context of cancer and has been reported as an oncogenic factor in various cancer types, including breast cancer." (PMID 40577453, 2025). "Accumulating evidence demonstrates that VIRMA is markedly overexpressed in multiple malignancies (e.g., hepatocellular carcinoma, breast cancer, colorectal cancer), where it drives tumor proliferation, invasion, and metastasis through m6A-dependent mechanisms." (PMID 40723784, 2025). "Recent studies have shown that VIRMA is upregulated in several malignancies such as breast cancer, lung cancer, germ cell tumor, and liver cancer, and is involved in tumor proliferation and metastasis." (PMID 36691046, 2023). "For instance, VIRMA promotes tumor development in breast cancer, while METTL3-mediated m6A modification of HDGF mRNA modulates the progression of gastric cancer." (PMID 36691046, 2023). "Only the full-length isoform of VIRMA is readily detected in control cells, indicating that VIRMA FL is the dominant isoform in breast cancer cells." (PMID 37208522, 2023). "We further observed significantly increased expression of VIRMA in breast cancers compared to matched normal breast tissues available from 79 patients in the TCGA cohort." (PMID 37208522, 2023). "While pre-clinical evaluation would be required to progress our discovery into clinical trials, we present here a potential novel strategy for treatment of one-sixth of breast cancer patients bearing amplification and overexpression of VIRMA in their tumours." (PMID 37208522, 2023). "The writer VIRMA was upregulated in both breast cancer cell lines, whereas HAKAI was only significantly upregulated in MCF7." (PMID 36725888, 2023). "By confirming that full-length VIRMA is enriched in the nucleus where m6A deposition occurs, while N-terminal VIRMA is generally cytoplasmic, our work explains why the previously reported role of N-terminal VIRMA in breast cancer is m6A-independent." (PMID 37208522, 2023). "We focused on breast cancer as it has the highest frequency of VIRMA amplification among the 27 cancers in the Cancer Genome Atlas Research Network (TCGA) cohorts." (PMID 37208522, 2023). "By determining the prevalence of VIRMA gene alterations and investigating the role of distinct VIRMA isoforms in breast cancer, we identify a unique m6A-dependent oncogenic role of full-length VIRMA under optimal cell growth conditions." (PMID 37208522, 2023). "Overall, our results demonstrate that overexpression of full-length VIRMA is necessary to enhance growth and colony formation of breast cancer cells in vitro and in vivo." (PMID 37208522, 2023). "Our results suggest that VIRMA overexpression sensitizes breast cancer cells to induce death via enhanced UPR and ER stress, while the opposite effect was observed with VIRMA depletion." (PMID 37208522, 2023). "No increases in METTL3, METTL14 and WTAP protein levels were detected in VIRMA FL-transduced HS578T cells that already express high levels of endogenous full-length VIRMA or in breast cancer cells overexpressing VIRMA N-term compared to control cells." (PMID 37208522, 2023).
breast carcinoma (continued). "Consistent with VIRMA being an essential protein for cell survival, the growth and colony-forming capacity of breast cancer cells were markedly perturbed consequent to VIRMA depletion in vitro." (PMID 37208522, 2023). "The cell cycle pathway played a significant role in the oncogenic activities of VIRMA, and ranked in the top two in breast cancer cell RIP-seq." (PMID 33731118, 2021). "High expression of VIRMA has been verified to predict poor survival in multiple cancers, such as breast cancer, liver cancer, kidney cancer and prostate cancer." (PMID 33731118, 2021). "Reverse experiments, RIP-seq, and RT-qPCR confirmed that CDK1 is the main target of VIRMA in breast cancer." (PMID 33731118, 2021). "VIRMA was found to be highly expressed and to predict poor overall survival (OS) in breast cancer, liver cancer and kidney cancer." (PMID 33731118, 2021). "The functions of VIRMA in breast cancer tumorigenesis and the related mechanisms have been previously reported." (PMID 33731118, 2021). "VIRMA facilitated breast cancer by regulating the CDK1 mRNA expression in an m6A-independent manner." (PMID 33731118, 2021). "Based on our results, a logical next step is to determine whether VIRMA-overexpression sensitizes breast cancer cells to these compounds." (PMID 37208522, 2023). "Our findings indicate that VIRMA overexpression in breast cancer may be an “Achilles Heel” that could be exploited for precision treatment of cancer cells with chemotherapeutic agents that trigger UPR and ER stress response." (PMID 37208522, 2023). "We show that VIRMA is amplified and overexpressed in 15–20% of breast cancers." (PMID 37208522, 2023). "To confirm the role of VIRMA overexpression in breast cancer, we expressed the HA-tagged full-length VIRMA (VIRMA FL) and the VIRMA N-terminal isoform (VIRMA N-term) in breast cancer cell lines bearing low (SKBR3 and AU565), intermediate (MDA-MB-231) and high (HS578T) endogenous levels of VIRMA." (PMID 37208522, 2023). "However, as full-length VIRMA is the dominant isoform in breast cancers, its overexpression and impact on m6A changes is likely to be more relevant to the development and maintenance of breast cancer than N-terminal VIRMA." (PMID 37208522, 2023). "Whether overexpressing the full-length VIRMA affects breast cancer pathology warrants an investigation." (PMID 37208522, 2023). "However, in breast cancer cells overexpressing full-length VIRMA, hypoxia and endoplasmic reticulum (ER) stress enhance an m6A-dependent unfolded protein response (UPR) and decrease cell viability." (PMID 37208522, 2023). "The high expression of VIRMA also predicted poor OS in patients with breast cancer." (PMID 33731118, 2021). "Recently, a new research indicates the oncogenic role of VIRMA in breast cancer." (PMID 32612834, 2020). "However, full-length VIRMA overexpression has minimal impact on the expression of other core components of the m6A-methyltransferase complex, indicating the possibility that full-length VIRMA has other m6A-independent role in breast cancer." (PMID 37208522, 2023). "Thus, the unexpected discovery that VIRMA-overexpressing cancer cells are more sensitive to UPR presents a previously undescribed “Achilles Heel” of breast cancer subtypes that may be useful for the development of precision intervention." (PMID 37208522, 2023). "Besides confirming recent reports that VIRMA overexpression promotes breast tumourigenesis and confers poorer overall survival, we reveal that VIRMA amplification affects all subtypes of breast cancer." (PMID 37208522, 2023). "Thus, our results indicate that increased expression of VIRMA may promote the expression of m6A-methylated NEAT1 that in turn triggers oncogenicity of breast cancer cells in vitro." (PMID 37208522, 2023). "In addition, 5′-fluorouracil (5-FU) could decrease the expression of VIRMA and its downstream target in breast cancer cells." (PMID 33731118, 2021).
breast carcinoma (continued). "Mechanistically, we reveal that VIRMA overexpression upregulates the m6A-modified long non-coding RNA, NEAT1, which contributes to breast cancer cell growth." (PMID 37208522, 2023). "Other subunits of METTL3 complex, namely WTAP, RBM15, KIAA1429 (also known as Virilizer homolog or VIRMA), and METTL14, displayed moderate-to-strong staining intensities in both normal and breast cancer tissues." (PMID 36289222, 2022). "KIAA1429, also called VIRMA, is mainly expressed in the cytoplasm in most human breast cancer cell lines and regulates m6A methylation modification as an RNA binding protein." (PMID 34044876, 2021). "Among them, the expression of RBM15, VIRMA, HNRNPA2B1, and YTHDF1/2/3 were significantly upregulated, but METTL3, METTL14, METTL16, WTAP, FTO, YTHDC1, and EIF3A had lower expression in breast cancer compared to normal samples." (PMID 34804948, 2021). "And the ability of 5′-fluorouracil (5-FU) to reduce the expression of VIRMA and CDK1 has been certified, which offers a possible treatment for breast cancer." (PMID 32612834, 2020). "Compared to control cells, overexpression of VIRMA N-term did not alter cell proliferation and clonogenicity in all four breast cancer cell lines examined." (PMID 37208522, 2023). "According to this research, the up-regulated VIRMA targets its downstream mRNAs like cyclin-dependent kinase 1 (CDK1) mRNA and enhances its translation in an m6A-dependent way to promote the progression of breast cancer." (PMID 32612834, 2020). "Similarly, studies in breast cancer reveal opposing functions of m6A regulators YTHDF2 and VIRMA." (PMID 39085650, 2024). "Given that only VIRMA FL contributed to the phenotypic and m6A level changes in breast cancer cells, we determined whether VIRMA FL but not VIRMA N-term is enriched in the nucleus since this is where m6A methylation typically occurs." (PMID 37208522, 2023).
hepatocellular carcinoma (45 papers, 2019 to 2026). A malignant tumor that arises from hepatocytes. "In hepatocellular carcinoma, studies have linked CNV changes in genes such as KIAA1429 (also known as vir-like m6A methyltransferase-associated protein (VIRMA)) and METTL16 to hepatocellular carcinoma development, progression, and clinical prognosis." (PMID 41459114, 2026). "Globally, these findings indicate that VIRMA depletion mitigates cancer progression by decreasing m6A RNA methylation levels in PCa, similarly to other cancer types, such as gastric, breast and hepatocellular carcinomas." (PMID 32218194, 2020). "Indeed, in glioblastoma and hepatocellular carcinoma, METTL14 downregulation associated with m6A levels reduction, while VIRMA upregulation positively correlated with higher m6A levels, in both testicular germ cell tumors and prostate cancer." (PMID 35048498, 2022). "In most malignancies (e.g., pancreatic ductal adenocarcinoma [PDAC] and hepatocellular carcinoma [HCC]), VIRMA primarily localizes to the nucleus." (PMID 40723784, 2025).
gastric cancer (36 papers, 2019 to 2026). A primary or metastatic malignant neoplasm involving the stomach. "The VIRMA promoter contains a p65 binding motif, and in gastric cancer, p65 upregulates VIRMA expression by binding to its promoter." (PMID 40723784, 2025). "After combining the associated genes by RIP-seq and mRNA-seq, c-Jun was identified as potential downstream target directly regulated by VIRMA in gastric cancer." (PMID 33731118, 2021). "A higher expression of VIRMA was observed in gastric cancer tissues, as compared with their adjusted normal tissues, which was associated with tumor grade." (PMID 33731118, 2021). "LINC00968 could negatively regulate the expression of miR-3202, which further regulate VIRMA, the coding gene of KIAA1429, in gastric cancer cells." (PMID 40069867, 2025). "The knockdown of VIRMA could inhibit gastric cancer cell proliferation by arresting the cell cycle in vivo and in vitro." (PMID 33731118, 2021). "Therefore, LINC00968 was speculated to regulate the progression of gastric cancer cells via modulating the miR-3202/VIRMA axis and further regulating KIAA1429." (PMID 40069867, 2025). "LINC00968 contributes to the enhanced cell growth and metastasis of gastric cancer, which was mediated by KIAA1429-mediating m6A modification and the miR-3202/VIRMA axis." (PMID 40069867, 2025). "In conclusion, upregulated LINC00968 in gastric cancer served as a tumor promoter regulating cell growth and metastasis via modulating the miR-3202/VIRMA axis and regulating KIAA1429." (PMID 40069867, 2025). "The detection of mRNA levels of m6A-modified enzymes (METTL3, WTAP, METTL14, VIRMA, RBM15, FTO, and ALKBH5) in gastric cancer tissues and adjacent tissues showed that the mRNA level of METTL3 was significantly higher in gastric cancer tissues." (PMID 34394353, 2021).
liver cancer (30 papers, 2019 to 2025). An epithelial or non-epithelial malignant neoplasm that arises from the liver. "KIAA1429 [also named as Vir like M6A methyltransferase associated (VIRMA)] promotes liver cancer progression via m6A modification of the lncRNA GATA3." (PMID 32793593, 2020). "Furthermore, the abnormal expression of VIRMA is closely associated with the resistance of liver cancer to immunotherapy." (PMID 39911396, 2025). "In hepatitis B virus surface small antigen (SHBs)-induced liver cancer cells, SHBs upregulated VIRMA expression, mediating the m6A modification of CCR9 mRNA and enhancing its stability, thus promoting regorafenib resistance." (PMID 40723784, 2025). "In liver cancer, upregulation of VIRMA significantly promoted lactate production, ATP synthesis, and glucose uptake." (PMID 40723784, 2025). "Targeting VIRMA presents a potential strategy to enhance the efficacy of liver cancer immunotherapy." (PMID 39911396, 2025). "VIRMA regulated the migration and invasion of liver cancer by regulating the m6A modification of ID2." (PMID 33731118, 2021). "GATA3 was identified as the direct downstream target of VIRMA-mediated m6A modification in liver cancer through the combination of immunoprecipitation sequencing (RIP-seq), and high-throughput methylated RNA immunoprecipitation sequencing (MeRIP-seq)." (PMID 33731118, 2021). "VIRMA promoted cell migration and invasion in liver cancer by increasing the m6A modification of ID2 mRNA, which then led to the decrease in ID2 expression." (PMID 33731118, 2021). "Therefore, VIRMA affects liver cancer immune escape and treatment response via a variety of molecular pathways as a major regulator of m6A modification." (PMID 39911396, 2025). "Moreover, in liver cancers, overexpression of VIRMA facilitated cell invasion, and down-regulation of VIRMA inhibited the m6A modification for ID2 or GATA3 mRNAs." (PMID 37437245, 2023). "Therefore, VIRMA promote the growth, metastasis and malignant phenotypes of liver cancer cells by regulating the GATA expression, which is mediated by the m6A modification of GATA3 pre-mRNA." (PMID 33731118, 2021). "A higher expression of VIRMA was observed in liver cancer tissues, as compared with adjacent normal tissues, both in the TCGA database and clinical samples, which predicted poor OS and DFS in patients with liver cancer." (PMID 33731118, 2021). "In addition, VIRMA was highly expressed and predicted poor disease-free survival (DFS) in liver cancer and kidney cancer." (PMID 33731118, 2021).
colorectal cancer (16 papers, 2022 to 2025). A primary or metastatic malignant neoplasm that affects the colon or rectum. "Mechanistically, CAF‐derived EV‐packaged circTAX1BP1 is delivered to colorectal cancer (CRC) cells, where it binds to VIRMA and promotes its lactylation at lysine residue 1713 by recruiting AARS2." (PMID 41017455, 2025).
osteosarcoma (12 papers, 2020 to 2024). A usually aggressive malignant bone-forming mesenchymal neoplasm, predominantly affecting adolescents and young adults. "In osteosarcoma, upregulation of VIRMA was found to be associated with the activation of the Notch signaling pathway." (PMID 33731118, 2021). "VIRMA was upregulated and associated with unfavorable outcomes in patients with osteosarcoma." (PMID 33731118, 2021). "It was proven that miR-143-3p could suppress VIRMA expression by directly targeting its 3ʹ-UTR region in osteosarcoma cells." (PMID 33731118, 2021). "The overexpression of miR-143-3p could inhibit VIRMA expression in osteosarcoma cells." (PMID 33731118, 2021). "miR-143 and VIRMA may become potential predictive biomarkers in the treatment of osteosarcoma." (PMID 33731118, 2021). "It was revealed that VIRMA knockdown could suppress the expression of stem factors Notch1, Oct4, Nanog and CD44 in osteosarcoma cells, which suggested that VIRMA promoted osteosarcoma progression by activating Notch signaling pathway." (PMID 33731118, 2021).